CXCL10 (C-X-C motif chemokine ligand 10)
Diseases named in the same sentence as CXCL10 in open-access papers (continued):
Sharing a sentence is not in itself a finding about the gene and the disease.
COVID-19 (continued). "Our study also found 4 additional targets (CCL20, CSF3, CXCL1, CXCL10) with existing therapies that have yet to be trialed in the COVID-19 patient population." (PMID 34582497, 2021). "In patients with cytokine storm secondary to COVID-19, elevated serum cytokine levels are mainly related to IL-1β, IL-6, CXCL10, TNF-α, IFN-γ, macrophage inflammatory protein (MIP) 1α and 1β, and VEGF." (PMID 33669011, 2021). "Elevated serum levels of CXCL10 were consistently reported in patients with COVID-19, being positively correlated (together with CCL2) with increased disease severity and, more importantly with an increased risk of mortality." (PMID 33981314, 2021). "It is clear evidence that ACE2 and CXCL10 are crucial proteins contributing to the COVID-19 disease progression." (PMID 33585826, 2021). "Most notably, the CXCL10+ CCL2+ inflammatory macrophages predominate in the bronchoalveolar lavage of patients with severe COVID-19, and are also detected in synovial tissue affected by RA and inflamed intestine from patients with IBD." (PMID 33879239, 2021). "Levels of IL-6, IL-10, IL-15, IFN-γ, TNF-α, CCL2, CCL3, CCL4, CCL26, CXCL9 and CXCL10 were significantly elevated both in COVID-19 critical clinical condition and in MAS patients as compared to healthy controls." (PMID 34226537, 2021). "Our results showed that critically ill COVID-19 patients had increased serum levels of IL-1β, IL-1RA, IL-6, IL-9, and CXCL10, and lower levels of IL-2 and IL17A as compared to healthy volunteer donors." (PMID 33995342, 2021). "An elevated level of CXCL-10/IL-10 in the patients of COVID-19 at Wuhan further evidenced the exacerbation of the innate immune response." (PMID 34305892, 2021). "These algorithms analyzed the targets’ functional and topological similarity to established COVID-19 pathogenesis genes and both scored CXCL10 the highest priority drug target." (PMID 34582497, 2021). "In another study, plasma CCL3 and CXCL10 levels were higher in COVID-19 patients with pneumonia and hypoxia requiring oxygen supplementation compared to patients without pneumonia and patients with pneumonia but not experiencing hypoxia." (PMID 33613280, 2020). "The cytokine profile of sHLH is associated with the severity of COVID-19, which is characterized by increased interleukin (IL)-2, IL-7, GCSF, IP10 (CXCL10), MCF1 (CCL2), MIP1A (CCL3), and TNF-α." (PMID 32574260, 2020). "NFKB1, NFKB2, IRF1, and CXCR3 were specifically up-regulated in COVID-19, and CXCL10, STAT1, TLR4, and genes for class II HLA and immunoproteasome subunits were specifically up-regulated in influenza." (PMID 32651212, 2020). "The expression of several cytokines identified in the current study (i.e., IL1B, IL-6, TNF, CCL2, CXCL9, and CXCL10) were also seen in bronchoalveolar lavage (BAL) cells from COVID-19 patients, providing further support to our observation." (PMID 32882823, 2020). "Our results reveal distinct host inflammatory cytokine profiles to SARS-CoV-2 infection in patients, and highlight the association between COVID-19 pathogenesis and excessive cytokine release such as CCL2/MCP-1, CXCL10/IP-10, CCL3/MIP-1A, and CCL4/MIP1B." (PMID 32228226, 2020). "Positive correlations between the serum CXCL13 level and the levels of IL-6 and CXCL10 were also noted in COVID-19 patients." (PMID 32963357, 2020). "Among 41 hospitalized COVID-19 patients in Wuhan, China, all had elevated IL-1B, IP10/CXCL10, and MCP1/CCL2." (PMID 32545518, 2020). "Follow-up analysis of COVID-19 patients demonstrated that humoral immune responses were positively correlated with the levels of IL-6, C-X-C motif chemokine 10 (CXCL10), and C5a." (PMID 32963357, 2020). "Factor 4 associated: outcomes (duration of MV, ICU and hospital length of stay, which were higher in COVID-19 patients at 30 days) and only GM-CSF, CXCL10 and INF-α levels." (PMID 33272291, 2020).
COVID-19 (continued). "Regarding the “HALLMARK_INFLAMMATORY_RESPONSE” gene set, MAFB and MAF were found to oppositely regulate the expression of a cluster of chemokine-encoding genes (CXCL10, CCL2, CCL7, CXCL9) that are associated to the COVID-19 “cytokine storm”." (PMID 33312178, 2020). "The chemokine CXCL10 has been observed to play a key role in recruiting of inflammatory cells to the site of inflammation and its role in COVID-19 induced cytokine storm has been shown in both experimental model and patients." (PMID 33569053, 2020). "CXCL10 (IP-10), IL-8, and IL-6 were elevated in acute COVID-19 (p < 0.0001, p < 0.05, p < 0.001) and correlated with disease severity, consistent with large cohort studies of plasma cytokines." (PMID 33010815, 2020). "Among them, we found that CXCL10 was the most likely to account for the protracted nature of COVID-19 ARDS in both the systemic and the alveolar compartments." (PMID 33138839, 2020). "Studies also suggested elevated levels of IL-8, MCP-1, IFN-γ, CXCL9, CXCL10 and GM-CSF in COVID-19 patients regarding triggering the neuronal manifestations." (PMID 33708124, 2020). "COVID-19 severity is linked to elevated levels of inflammatory mediators, including cytokines (e.g., IL-2, IL-7, IL-10, IFN-γ, and TNF-α) and chemokines (e.g., G-CSF, MCP1, MIP1α, and CXCL10), as well as markers like C-reactive protein, ferritin, and D-dimers." (PMID 40649865, 2025). "Increased levels of interleukins (IL-1 α, IL-7, IL-17, and IL-18) and chemokines (CCL11, and CXCL1) were found only in the COVID-19-only, whilst PLWH/COVID-19, had increased levels of four different interleukins (IL-5, IL-6, IL-9, and IL-15) and one chemokine (CXCL10) compared to COVID-19-only." (PMID 41516165, 2025). "High CXCL10 levels have been linked with the development of acute kidney injury in pediatric sepsis patients, progression to septic shock, ARDS and lung fibrosis in COVID-19." (PMID 40076848, 2025). "This is consistent with reports of elevated CXCL10 in the brains of COVID-19 patients." (PMID 41156605, 2025). "Also, in PLWH/COVID-19, serum levels of a different set of interleukins (IL-5, IL-6, IL-9, and IL-15) and chemokine CXCL10 were upregulated." (PMID 41516165, 2025). "Serum CXCL10 was increased in all COVID-19 patients compared to controls." (PMID 39882243, 2024). "We can speculate that an initial short-lived CXCL10 response may be beneficial whereas persistently sustained CXCL10 amounts, as seen in COVID-19 patients, may contribute to dysregulated inflammation and ARDS development." (PMID 39803542, 2024). "For instance, interventions designed to inhibit the signaling pathways of CCL2 and CXCL10 may help to reduce excessive immune cell recruitment and activation, thereby limiting inflammation and preventing the escalation of lung injury in COVID-19 patients." (PMID 39203987, 2024). "Moreover, the roles of CCL2 and CXCL10 extend beyond simple chemotaxis; they are intricately involved in the pathophysiological mechanisms that drive the progression of COVID-19 to its more severe forms." (PMID 39203987, 2024). "Moreover, in COVID-19 patients, increased mRNA expression levels of CXCL10, CCL2, and TNF were correlated with an increased number of MKs27,28." (PMID 38519457, 2024). "Consistent with this, the reported COVID-19-induced disruptions in gut microbial function were associated with disease severity and the inflammatory response, including elevated levels of pro-inflammatory cytokines and CXCL-10, a chemokine characteristic of COVID-19." (PMID 39519526, 2024). "However, an IFNγ-induced signature is probably present in COVID-19, since CXCL10 (in common with CXCL9), an important IFNγ-induced chemokine, is highly detectable, as previously observed in several IFNγ-mediated syndromes." (PMID 39882243, 2024).
COVID-19 (continued). "The complications, severity, and mortality of COVID-19 patients are caused by excessive activation of cytokines (IL-1, IL-6, TNF-a, CCL2, and CXCL10, etc.), namely cytokine storm, which is remarkably similar to the pathogenesis of immune disorders in RA patients." (PMID 38378889, 2024). "Levels of CCL2 and CCL8 in BAL fluid as well as CXCL10 in plasma samples collected during the first 48 hours of intubation were higher in patients with COVID-19 relative to all other groups, with the exception of patients with other viral pneumonias (q < 0.05, Mann-Whitney)." (PMID 38502186, 2024). ", systemic HG, and ASV039 (Corynebacterium matruchotii) and, along with CXCL10/IP-10, these five nodes represent 59.1% of the total predictive capacity in submodel y1 in classifying whether a patient has been diagnosed with COVID-19 at an accuracy of 99.5%." (PMID 38617584, 2024). "Elevated levels of CXCL10 were observed in COVID-19 and were associated with a severe course and progression of the disease, predicting ARDS and neurological complications (Yakutia has higher levels of COVID-19)." (PMID 39769502, 2024). "Consequently, CXCL10 has been proposed as a prognostic marker and a potential mediator of COVID-19-induced ARDS." (PMID 39803542, 2024). "Finally, qRT-PCR analyses revealed that the pro-inflammatory cytokines CCL2 and CXCL10 whose expression is correlated with severe COVID-19 (reviewed in52) were significantly reduced in KYA1797K and E7449-treated animals." (PMID 40295745, 2024). "Serum levels of CXCL10 appeared to increase with the severity of COVID-19." (PMID 39882243, 2024). "These intercellular interaction analyses computationally infer the possibility that dysfunction of ncMono and the consequently reduced interaction of CXCL10/CXCR3 might be one of the factors responsible for driving COVID-19 severity." (PMID 37095364, 2023). "In general, CXCL10 levels in the serum were higher than in the CSF for the entire COVID-19 cohort (serum = 405.2 pg/ml, 32.8–234.3 pg/ml versus CSF = 226.7 pg/ml, 49.1–622.1 pg/ml) resulting in CSF/serum ratios in between 0.53–0.59 pointing at a cytokine origin from outside of the CNS." (PMID 36759861, 2023). "We treated THP-1 macrophages with purified S1 protein to evaluate the expression of the pro-inflammatory cytokines TNF-α, CXCL10, and IFN-γ due to their association with hyperinflammation in SARS and COVID-19 patients, as well as the antiviral cytokine IFN-β, since it restricts SARS-CoV-2 infection." (PMID 36992463, 2023). "Elevated levels of CXCL10 and IL-6 has been shown to correlate with severe COVID-19." (PMID 37507719, 2023). "In a recent study, it has been reported that depletion of gut microbiota in COVID-19 cohort was linked with increasing concentrations of TNF-α, CXCL10, CCL2 and IL-10 indicating that these taxa might have a role in reducing the ARDS associated cytokine storm." (PMID 37161621, 2023). "It has been reported that CXCL10/IP-10 is elevated in COVID-19 patients and may be a predictor of COVID-19 outcome." (PMID 36851770, 2023). "In COVID-19 non-survivor genes related to neutrophil chemotaxis and migration, including CXCL10, CCL20, CCL8, C3AR1, CCL2, VAV3 are significantly upregulated; increased neutrophil is a typical signature of COVID-19 and closely linked to fatality, as already reported by other studies." (PMID 37949875, 2023). "Cytokine screening analysis performed simultaneously with metabolomic analysis revealed that CXCL10 levels were specifically elevated and significantly positively correlated with blood amino acid catabolite concentrations during the early stages of COVID-19 in severe outcome patients." (PMID 38123556, 2023). "Indeed, previous studies have defined IL-6, IL-8/CXCL8 and, IP-10/CXCL10 as early prognostic parameters of COVID-19 severe disease." (PMID 36997530, 2023).
COVID-19 (continued). "Furthermore, elevated levels of chemokines that contribute to cancer development, such as CCL2, CCL4, CXCL8, CXCL9 and CXCL10 have been found in COVID-19." (PMID 37753372, 2023). "Additionally, the PCA coordinates obtained from the 3rd trimester demonstrated that several soluble mediators were vectors related to convalescent COVID-19 in pregnant women, except for CXCL10, IL-1β, TNF-α, IFN-γ, PDGF and GM-CSF." (PMID 37122732, 2023). "Severely ill COVID-19 patients display lung tissue damage associated with cell death and pathologic inflammation, which are linked to enhanced pro-inflammatory cytokine and chemokine levels (e.g., TNF-α and CXCL10)." (PMID 36992463, 2023). "Finally, we explored the intercellular interactions centered on CXCL10 in ncMono, which was significantly downregulated in severe COVID-19." (PMID 37095364, 2023). "Similarly to COVID-19, in other ARVIs, the levels of IFNγ-inducible CXCL10 in BAL and plasma correlate with the severity of the disease." (PMID 37214455, 2023). "Among the cytokines analyzed in response to S-peptide, some of them such as TNFα, IL-6, IL-2, IFNγ, or CXCL10 were differentially produced between naïve subjects and subjects recovered from COVID-19 early after the second vaccination dose (sample 2), with higher levels in the former group." (PMID 37153580, 2023). "CXCL10 is the most widely studied chemokine in patients with COVID-19." (PMID 37493737, 2023). "We also observed a > 2-fold increase in IL-15 in COVID-19 patients (2.3 ± 0.1 for controls vs. 5.7 ± 0.8 pg/mL for COVID-19 patients) and a 10-fold increase in CXCL10/IP-10 over controls (401.5 ± 75.5 pg/mL controls vs. 4257.0 ± 1383.1 pg/mL COVID-19 patients, p < 0.001)." (PMID 36851770, 2023). "Additionally, other inflammation-related molecules shared between OA and COVID-19, such as these encoded by HIF1A, CXCL10, and CTSB, contribute to the same pathophysiological bonfire." (PMID 38020136, 2023). "Moreover, CXCL10/IP-10 in blood has been shown to correlate with increased disease severity in COVID-19." (PMID 36851770, 2023). "Analysis of CNAs in TMPRSS2 and CXCL10 may help in assessing the clinical features of COVID-19 patients with aggressive or indolent prostate cancer." (PMID 36239108, 2022). "In this review paper, we focused on the changes in concentration and role of CXCL10 in COVID-19." (PMID 35409036, 2022). "Therefore, cytokine storm manifesting elevated levels of CXCL10 and coronavirus neuroinvasion are a possible reason for neurological manifestations and COVID-19-related severe nervous system complications." (PMID 35409036, 2022). "Furthermore, Ruxolitinib, a JAK1/JAK2 inhibitor acting downstream of JAK-dependent chemokines/cytokines such as IFN-γ, IL-1β, IL-6, TNF, G-CSF, CXCL9, and CXCL10, has shown promising results in treating COVID-19." (PMID 35269470, 2022). "So, knowing that CXCL10 through CXCR3 is associated with inflammatory diseases, it has been suggested that the CXCL10–CXCR3 axis may be probably involved in development of COVID-19." (PMID 35409036, 2022). "Similarly, Th1-type chemokines, CXCL9 and CXCL10, were elevated in the patient with COVID-19 vaccine-related myopericarditis compared to healthy and vaccine controls." (PMID 35251049, 2022). "They showed that NP CXCL10 had a good overall performance and their outcomes show how biomarker-based screening can be used to leverage the existing PCR testing potential to rapidly permit the large scale testing for COVID-19." (PMID 36016187, 2022). "Among elevated plasma inflammatory mediator levels; CRP, ICAM-1, SAA, VCAM-1, CXCL10, IL-7, IL-10 and Flt-1 may suggest the severity of COVID-19." (PMID 35958594, 2022). "Interestingly, CXCL10 levels were reported to be significantly reduced upon improving clinical outcomes in hospitalized COVID-19 patients." (PMID 36366543, 2022).
COVID-19 (continued). "Thus, correlations were performed in the current investigation, implying that plasma levels of CRP, SAA, IL-6, CXCL10, VCAM-1, and IL-10, among the linked, exhibit a significant and beneficial association with COVID-19 patient progression." (PMID 35958594, 2022). "Also, another study revealed that patients with a severe course of COVID-19 have increased levels of CXCL10." (PMID 35409036, 2022). "Thus, the present study points to an important role of CXCL10 for induction of stress hyperglycemia in COVID-19." (PMID 36059840, 2022). "This suggests that patients with NAFLD and COVID-19 might have different regulations of CXCL10 secretion." (PMID 35743825, 2022). "Consequently, the use of CXCL10 as an independent predictor for COVID-19 progression was suggested since it was correlated with ARDS in critically ill patients and severe cases." (PMID 36366543, 2022). "Furthermore, higher mortality was reported in COVID-19 patients with a dramatic increase in CXCL10 levels compared with severe and mild COVID-19 patients." (PMID 36366543, 2022). "Additionally, the level of multiple chemokines (IL-12p40, CCL2, CCL7, CXCL10, and M-CSF) was significantly increased in fatal COVID-19 cases." (PMID 35386707, 2022). "Interestingly, we noted that cytokines widely associated with COVID-19 severity such IL6, CXCL10, and TNF showed multiple but modest correlations with clinical parameters in all groups, likely reflecting their multifunctional role in disease development." (PMID 34957382, 2022). "Moreover, monocytes fall into clearly distinct clusters, annotated by their highly expressed markers, IL-6+ monocytes, GPBAR1+ monocytes and CXCL10+ monocytes, and were mostly derived from neonates with COVID-19." (PMID 34937051, 2022). "Based on these facts, it is plausible to state that because ACE2, TMPRSS2, and CXCL10 are commonly contributing molecules in both the pathogenesis of SARS-CoV-2 and PRAD, men could be more susceptible to acquiring COVID-19." (PMID 36239108, 2022). "Besides these inflammatory conditions, CXCL10/IP10 levels were evaluated among adult patients with COVID-19 and were found to be a good predictor of the outcome." (PMID 35268506, 2022). "Finally, we found that TMPRSS2 and CXCL10 are two putative biomarkers responsible for the increased vulnerability and fatality of prostate cancer patients to COVID-19." (PMID 36239108, 2022). "In this respect, CXCL10 is considered to be a key immune factor in the cytokine storm observed in patients with coronavirus disease 2019 (COVID-19) and might be predictive of the clinical outcome." (PMID 36059986, 2022). "However, galectin-9 plasma levels also correlated with pro-inflammatory mediator secretion (IL-6, TNFα, CXCL10) in dengue and COVID-19 infected patients." (PMID 36142892, 2022). "In addition, higher circulation levels of CXCL10 can activate Th1 cell function, and it has been shown to be highly correlated with COVID-19-induced ARDS in clinical and experimental studies." (PMID 35464491, 2022). "Levels of IL-6, CXCL10, CXCL11, IFNγ and MCP-3 were > fourfold higher in the serum of patients with COVID-19 versus healthy controls and linked with observations of inflammatory and viral-induced interferon response genes detected in nasopharyngeal swab samples from the same patients." (PMID 35303909, 2022). "Similar to SARS and MERS, CXCL10 is significantly elevated in COVID-19 patients." (PMID 35062368, 2022). "So, it has been suggested that abnormal CXCL10 levels at hospital admission may predict COVID-19 outcome." (PMID 35409036, 2022). "Increased concentrations of CXCL10 were observed in COVID-19." (PMID 35409036, 2022). "Published studies revealed that CXCL10 may be a very good predictive biomarker of patient outcome in COVID-19, and that markedly elevated CXCL10 levels are connected with ARDS and neurological complications." (PMID 35409036, 2022).